IL6 (interleukin 6)
Diseases named in the same sentence as IL6 in open-access papers (continued):
Sharing a sentence is not in itself a finding about the gene and the disease.
diabetes (continued). "The activation of NF-κB leads to the transcription of pro-inflammatory cytokines, such as tumor necrosis factor-α (TNF-α), interleukin-6 (IL-6), and interleukin-1β (IL-1β), which in turn can further activate NF-κB, intensifying the inflammatory response and hastening the progression of diabetes." (PMID 38671942, 2024). "The significantly increased levels in the hemodialyzed diabetic patient group compared with the non-diabetic hemodialyzed patients allowed for us to conclude that IL-6 induces intense proinflammatory trans-signaling in dialyzed patients, especially those with diabetes." (PMID 38921685, 2024). "TNF, IL1, IL6, IL18, IL8, intracellular and vascular cell adhesion molecules, matrix metalloproteinases, and monocyte chemoattractant protein 1 (MCP-1) are all upregulated in diabetes and have been connected to its associated complications." (PMID 37047011, 2023). "However, further longitudinal studies with a larger sample size are required to confirm the impact of periodontal disease with diabetes on IL-6 levels with diabetes mellitus." (PMID 37854742, 2023). "We determined the level of tissue cytokines (TNF-α and IL-6) in the brain and liver, seeing as alloxan-induced diabetes is characterized by cytotoxicity in the pancreas, brain (neuronal degeneration and necrosis), kidney (nephrosis, nephritis), and liver (hepatitis)." (PMID 37629665, 2023). "IL-6, a protein, is produced by numerous cells and is elevated with the severity of diabetes." (PMID 37894687, 2023). "The interaction between inflammation, T2D, and CVD might be explained by the co-signaling of IL-1β and IL-6 in diabetes and atherosclerosis." (PMID 37113481, 2023). "There is sufficient evidence to show that compared to patients with simple periodontitis, patients with combined diabetes and periodontitis have increased proinflammatory cytokines IL-6 and IL-1β, and there is a quantitative relationship between glycemic control and these cytokines." (PMID 37664859, 2023). "In the sample overall, MD was associated with higher IL-6 and blood pressure, but not other indicators of diabetes risk." (PMID 37008275, 2023). "In summary, the application of cMDSCs propagated from GM-CSF, IL-6, and IL-1β cytokines can improve renal function and increase insulin secretion from pancreatic islets, thereby prolonging the diabetes-free survival of NOD–SCID mice after treatment with T cells." (PMID 37296628, 2023). "Experimental evidence found that patients with diabetes have chronic low-grade inflammation marked by higher levels of pro-inflammatory mediators including C-reactive protein, interleukin 6, and tumor necrosis factor alpha, as well as abnormal cytokine-secreting cells." (PMID 37478111, 2023). "In patients with OSA and diabetes, increased IL-6 levels were observed." (PMID 36769452, 2023). "In the last few decades, IL-6 has been linked to various diseases, such as rheumatoid arthritis (RA), diabetes, cancer and multiple sclerosis (MS), and the overall concentration of IL-6 is elevated in acute and chronic inflammation and is a significant driver of autoimmune diseases." (PMID 37759507, 2023). "Diabetes not only impairs antioxidant integrity but also initiates neuroinflammatory reactions by activating the nuclear transcription factor NfκB, which stimulates IL6, IL-1β, and TNF-α pro-inflammatory cytokines." (PMID 38105928, 2023). "Hesperidin could attenuate inflammatory and oxidative damage induced by hyperglycemia by reducing malondialdehyde, nitric oxide, and IL‐6 concentrations and improving adiponectin expression and glutathione levels in rodent models of diabetes." (PMID 38107097, 2023). "IL-6 mRNA levels increased in PCOS patients, and, as treated with an anti-inflammatory agent such as resveratrol, their expression seemed to decrease, reducing the diabetes risk in patients." (PMID 36677054, 2023). "Increased levels of IL-6 are related to insulin resistance and inflammation in β-cells in Diabetes." (PMID 37575261, 2023).
diabetes (continued). "IL-6 could be better marker than CRP for the inflammation seen with diabetes and even in co-morbidity, more so as IL-6 could differentiate good from poor glycemic control." (PMID 37545969, 2023). "Consequently, this modulation influences the severity of various ailments such as Alzheimer’s disease, myocardial disorders, and diabetes by impacting the expression of pro-inflammatory cytokines like IL-1β, IL-6, TNF-α, and type 1 interferons." (PMID 38001481, 2023). "Moreover, a study reported that hesperidin had significant role in the suppression of inflammatory markers such as tumor necrosis factor alpha (TNFα) and interleukin 6 (IL-6) in patients with type 2 diabetes mellitus." (PMID 37082190, 2023). "Based on the present study findings, the Interleukin 6, is one of the powerful predictors of coronaryartery disease in patients with type 2 diabetes mellitus, since these values are significantly increased in later stages of T2DM and CADwhen compared to newly diagnosed CAD patients." (PMID 38250529, 2023). "Diabetes’ duration is a clinical risk factor for DR and our data suggest that T1D duration has a positive correlation with PBMC-derived IL-6 which may promote DR pathology." (PMID 36766809, 2023). "Similarly, weekly intraperitoneal injections of 50 μg/mL of anti-IL-17A significantly decreased (p < 0.05) diabetes-mediated IL-1β, IL-6, TNF-α, and ZO-1 degradation in the retinas of db/db-Type II diabetic mice 2 months post-diabetes." (PMID 36674854, 2023). "In this sense, one may hypothesize that the increased level of IL-6 - or other inflammatory mediators involved in the impaired glucose regulation state – can play a role linking together diabetes mellitus and hypocalcemia, as emerged in our population." (PMID 36350462, 2023). "A similar positive association has been previously reported between systemic inflammation, i.e., increased serum cytokine IL-1 β, IL-3, INF- γ, and GADA levels in patients with both types of diabetes and significantly higher IL-6 and IL-15 concentrations in autoimmune diabetes." (PMID 37025699, 2023). "Similarly, metformin significantly (p < 0.05) decreased the levels of hepatic TNF-α and IL-6 by about 84% and 87%, respectively, in rats with diabetes in comparison to only rats with diabetes." (PMID 37280499, 2023). "However, 6 months after the induction of diabetes, the expression levels of Ccl2, Il1b, Il6, Tnf, Tgfb and Inos (Nos2) were significantly higher in the Il33−/− retina than in the WT retina." (PMID 37671525, 2023). "In this work, we discovered that quercetin and kaempferol had antidiabetic effects via suppression of IL-1β, IL-6, and IKKβ, suggesting that they may be promising candidate for the treatment of diabetes." (PMID 36826001, 2023). "In per-patient adjusted analyses, cardiovascular disease (118·78 [95% CI 7·78–1814·67]), diabetes (3·14 [CI 2·19–4·50]), IL-6 inhibitor use (1·70 [CI 1·12–2·56]), and antibiotics use (2·70 [1·28–5·70]) were associated with increased odds of being infected with a resistant pathogen." (PMID 36736332, 2023). "Proinflammatory cytokines such as tumor necrosis factor (TNF), IL-1, IL-2, and IL-6 are overexpressed in diabetes and Alzheimer’s disease patients’ brains, indicating the role of inflammation in neuronal damage, likely through the downregulation of the pro-inflammatory microglial function." (PMID 35682821, 2022). "Overall, c-miR-21, SOD, CAT, and IL-6 had high predictive values for diabetes diagnoses." (PMID 36139749, 2022). "However, when we analyzed three M1 cytokines, IL-1β, IL-12, and IL-6, we found that diabetes microglia had significantly lower levels of IL-1β, significantly higher levels of IL-12 and unaltered levels of IL-6." (PMID 35935990, 2022). "There have been many studies demonstrating an association between CRP and IL-6 and incident diabetes, and several reported this to be independent of adiposity or insulin resistance." (PMID 36407366, 2022).
diabetes (continued). "Data shows that the raised levels of blood pressure and diabetes may be provoke for inflammatory cytokines IL-6, hs-CRP, and uric acid which are promising potential biomarkers for detecting CAD in individuals." (PMID 37323554, 2022). "Type 2 diabetes mellitus (T2D) is the result of a dysregulation of insulin production and signalling, leading to an increase in both glucose concentration and pro-inflammatory cytokines such as interleukin (IL)-6 and tumour necrosis factor (TNF)-α." (PMID 36463286, 2022). "Patients with diabetes and hypertension showed elevated IL-6, CRP, and CXCL-10 (p < 0.001)." (PMID 35967091, 2022). "Supporting this notation, a study found that the administration of low-dose pulsatile IL-6 could exert neuroprotection against diabetes-induced peripheral neuropathy." (PMID 36676049, 2022). "However, the bone loss, probing depth, plaque index and levels of IL-6 and TNF-α in the PICF were statistically higher in prediabetes as compared to non-diabetes, implying that hyperglycemia induces irreversible peri-implant bone alterations." (PMID 36557041, 2022). "However, when an inter-group comparison was made between non-diabetes and diabetes, the values of both IL-6 and TNF-α were significantly different among both the NDISCs and NDISPs." (PMID 36557041, 2022). "Diabetes is also associated with upregulation of vascular inflammation including the induction of pro-atherogenic mediators in the thoracic aorta, including the adhesion molecule (VCAM-1) and inflammatory markers (TNFα, IL-6, MCP-1, CD11b, and KLF3)." (PMID 35624851, 2022). "IL-6 increases significantly in painful diabetic neuropathy patients compared to patients with diabetes with painless neuropathy and thus may have a role in the pathogenesis of pain in DPN." (PMID 35155045, 2022). "The results showed that the GMP intervention group could further reduce the inflammatory reaction induced by diabetes by reducing the levels of IL-6, TNF-α, and CRP and increasing IL-10." (PMID 35399678, 2022). "However, patients with diabetes were characterized by statistically significantly higher body weight, and higher IL-6, fasting glucose, glycated hemoglobin levels than patients without type II diabetes (data not shown)." (PMID 34813039, 2022). "A consistent finding in our study, regardless of HIV or diabetes comorbidity, was the association between baseline IL-6 with all-cause mortality." (PMID 34711538, 2022). "miR-21, SOD, CAT, and IL-6 revealed a high predictive value for diabetes diagnosis." (PMID 36139749, 2022). "In contrast, IL-6 was predominately associated with maternal chorioamnionitis, rather than birth weight or diabetes." (PMID 35197933, 2022). "They demonstrated that median IL-6 and TNF-α were higher in diabetes compared to non-diabetes (p < 0.01), suggesting that diabetes was strongly associated with elevated levels of IL-6 and TNF-α." (PMID 36140983, 2022). "In the process of atherosclerosis, inflammation is one of the important pathological factors in which C-reactive protein (CRP), TNF-α, IL-6, and other inflammatory cytokines play an important role in the occurrence and development of large vessel atherosclerosis in diabetes." (PMID 36212957, 2022). "In a study that examined the effect of pomegranate juice supplementation on inflammatory markers in patients with diabetes, it was demonstrated that taking 250 mL of pomegranate juice daily for 12 weeks led to a significant reduction in IL-6 and serum hs-CRP levels." (PMID 36330147, 2022). "Whether HuR exerts a pro-inflammatory, pro-diabetic role through stabilization of IL-6 mRNA in diabetes is worth exploring." (PMID 35597446, 2022). "Interleukin 6 (IL‐6) may be a key early indicator of DR as higher circulating levels were detected in children with DR, who, crucially, will have diabetes and DR for much shorter times than adults." (PMID 34269526, 2022).
diabetes (continued). "Indeed, targeting classical inflammatory molecules including IL-1, IL-6 and TNF have been shown to reduce the risk of diabetes and improve insulin sensitivity in some studies, although with variable effects." (PMID 35480482, 2022). "Finally, we confirmed that inhibition of GC synthesis reduced the diabetes-increased infarct size with reduced IL-6 expression." (PMID 35784349, 2022). "Moreover, ZER attenuated the upregulation of tumor necrosis factor (TNF-α), interleukin-1 (IL-1), and interleukin-6 (IL-6) induced by diabetes." (PMID 35949312, 2022). "Similarly, the median of IL-6 in women having diabetes was about 2.0 pg/mL, compared to women free of diabetes (1.38 pg/mL)." (PMID 34991564, 2022). "However, at fasting, myeloid dendritic cells in individuals with diabetes, exhibited higher LPS-induced IL-6 and IL-1 beta production than controls." (PMID 36619534, 2022). "After that, multivariate analysis revealed that the independent risk factors for hospital mortality were increased age, diabetes, chronic renal diseases, decreased systolic blood pressure (SBP), and elevated fibrinogen, interleukin 6 (IL-6) and blood urea nitrogen (BUN)." (PMID 36117161, 2022). "Therefore, all variables with a p-value ≤0.2, which were family history of diabetes, physical activity, alcohol consumption and IL6 inflammatory biomarker, were subjected to poison regression analysis with robust variance." (PMID 36561566, 2022). "The prognosis of patients with AIS at 90-days after IVT was used as the dependent variable, and age, smoking, hypertension, diabetes, coronary artery disease, hyperlipidemia, atrial fibrillation, IL-6, MMP-9, ADAMTS13, TRX, TNC, and GSN were considered independent variables." (PMID 36127663, 2022). "Interestingly, there was a significant reduction in diabetes-induced systemic oxidative stress following the inhibition of pro-inflammatory trans-signaling of IL-6." (PMID 36676049, 2022). "Here, we observed a marked alteration of the major pro- and anti-inflammatory cytokines involved in diabetes pathogenesis, including IL-10, IL-6, and TNF-α in the diabetic rats, which significantly attenuated after treatment by heat-killed Actinomycetales species." (PMID 33880360, 2021). "For example, the level of serum IL-6 in DN patients is higher than that without DN patients and the risk of DN in type 2 diabetes mellitus (T2DM) patients with high IL-6 gene polymorphism is increased." (PMID 34054555, 2021). "In addition, persistent hyperglycemia due to diabetes induces IL-6- and IL-1β-mediated dysfunction of insulin secretion." (PMID 34836432, 2021). "Moreover, elevated levels of C-reactive protein (CRP), tumor necrosis factor-α (TNF-α), IL-6, IL-18, and IL-1β were reported among patients with type 2 diabetes mellitus displaying features of the insulin resistance syndrome." (PMID 34917685, 2021). "As prolonged inflammation and oxidative stress are linked to unsuccessful wound healing in patients with diabetes, we investigated the effects of PBM on the proinflammatory cytokines IL-6 and TNF-α, as well as the proinflammatory mediator cox-2 in diabetic wounded fibroblast cell culture models." (PMID 33628374, 2021). "Thus, more systemic inflammatory circulating markers such as IL-6, TNF-α, and CRP levels significantly increased and were detrimentally respective to the risk and the development of type 2 diabetes mellitus." (PMID 34917685, 2021). "Importantly, serum levels of IL-6 in patients with diabetes and SARS-CoV-2 infection were significantly higher than those in non-diabetic patients." (PMID 34690930, 2021). "This could explain the mechanism by which MSCs exert their hypoglycemic and cardioprotective effects by suppressing inflammatory markers, TNF-α and IL-6, that both play a role in the progression of diabetes and atherosclerosis." (PMID 33737713, 2021).
diabetes (continued). "Diabetes-mediated retinal inflammation is one of the first detectable retinal pathologies in this murine model, wherein hyperglycemia induces multiple inflammatory processes, including IL-6, IL-1β, and VEGF production." (PMID 34456740, 2021). "Furthermore, ADP, TNF-α and IL-6 still correlated independently with ANP (p < 0.05) after adjustment for the duration of diabetes and BUN." (PMID 34663293, 2021). "As AGRT1, IL6, NOS3 and TNFA genes are common candidates for diabetes and associated complications, drugs that target these might mitigate multiple risk factors simultaneously." (PMID 33820928, 2021). "Actually, they are reported to inhibit the production of key cytokines such as TNF-α (tumor necrosis factor-alpha) and IL-6 (interleukin-6), released in most inflammatory processes and involved in many diseases such as autoimmune ones, diabetes, atherosclerosis, and cancer." (PMID 35011233, 2021). "In our study, type 2 diabetes mellitus was found in 42 patients and high IL-6 levels in 27 of them." (PMID 33535417, 2021). "Conversely, Dnm3os knockdown with siRNAs in macrophages from diabetic db/db mice ameliorated the enhanced expression of inflammatory genes (Il6, Tnf, Itgax, and Nfkbiz) and phagocytosis of E.coli bioparticles, clearly supporting its role in diabetes-induced inflammation." (PMID 34234740, 2021). "However, participants with diabetes showed increased expression of 9 proteins, such as IL-6 and HGF." (PMID 34385358, 2021). "Metformin could not only improve autophagy and mitochondrial function in diabetes but also decrease inflammation by down-regulate pro-inflammatory cytokines, such as IL-6 and TNF-α." (PMID 33855034, 2021). "In addition, after adjusting for age, sex, smoking, BMI and diabetes duration, the levels of LDL-C, HbA1c, UACR, IL-6, and TNF-α are independent risk factors for painful DPN." (PMID 33777989, 2021). "The current results were in accordance with the role of IL6 in both diabetes and NFLD." (PMID 35154608, 2021). "At baseline, all the markers demonstrated a positive association with the prevalence of CKD, but at the 15-year follow-up, results showed only TNF-α and IL-6 were associated with the prevalence of CKD, which researchers attributed to other comorbidities such as diabetes and hypertension." (PMID 34068841, 2021). "In the absence of an immunostimulant, diabetes is associated with an increased pro-inflammatory cytokine response marked by increased secretion of IL-1, IL-6, IL-8 and TNF-α, which in turn play a more deleterious role in Covid-19 infection." (PMID 34090396, 2021). "However, the odds of having a heart attack in participants with diabetes increased by 20 fold in presence of high levels of triglycerides, TNFα and IL6 if coupled with low levels of HDL-C." (PMID 33510184, 2021). "However, no bDMARD has yet been recommended or approved for the treatment of diabetes, although a clinical trial to assess the potential efficacy of anti-IL-6 therapy (tocilizumab) in patients with type 1 diabetes is in progress." (PMID 32907617, 2020). "Multiple icv injections of AZD7545 (6.4 nM of CSF concentration), GSK2837808A (2 μM of CSF concentration) or oxamate (25 μg) significantly attenuated the diabetes-induced expression of proinflammatory cytokines Tnf-α, Il-1β, and Il-6 mRNAs, in the hypothalamus." (PMID 33219201, 2020). "Remarkably, ablation of astrocytic Pdk2 in the hypothalamus attenuated diabetes-induced local inflammation, characterized by increased levels of the inflammatory cytokines Tnf-α, Il-1β, and Il-6 mRNA, and proliferation and activation of GFAP-positive astrocytes and Iba-1-positive microglia." (PMID 33219201, 2020). "Interestingly, a reactive increase in IL-6 expression during acute inflammation is delayed in a mouse model of diabetes." (PMID 32365896, 2020). "Furthermore, in a mouse model of diabetes, the treatment with mangiferin reduced IL-6, TNF-α, and Il-1β expression by inhibiting PTEN/PI3K/Akt pathway." (PMID 32471207, 2020).